S100A9 (S100 calcium binding protein A9)
Diseases named in the same sentence as S100A9 in open-access papers (continued):
Sharing a sentence is not in itself a finding about the gene and the disease.
cancer (continued). "Previous studies have implied that S100A8 and S100A9 have a pathogenic effect in cancer progression in a concentration-dependent manner." (PMID 25673070, 2015). "Cell cycle kinases (e.g. CDC2, CDC5, CDC7 and CDC20) as well as AURKA and S100A9, which can all broadly be linked to cell cycle regulation and mitosis, were upregulated in the malignant tumors." (PMID 25226589, 2014). "In particular, S100A8 and S100A9 are the focus of intense research, as they are associated with several inflammatory diseases and cancer." (PMID 23626736, 2013). "S100A8 and S100A9 are Ca2+-binding proteins that are associated with acute and chronic inflammation and cancer." (PMID 23626736, 2013). "The association of S100A9 expression with different clinicopathological features and patient prognosis among a variety of cancer types suggests that the function of this molecule can be diverse." (PMID 22838504, 2012). "The S100A9 protein was originally discovered as an immunological protein in neutrophils and has more recently been associated with several forms of human cancer and inflammation-associated carcinogenesis." (PMID 22253789, 2012). "Protein S100-A9 belongs to the calgranulin B subgroup of the S100 family, and is mainly associated with acute/chronic inflammatory disorders and various cancers." (PMID 22860055, 2012). "Similarly, S100A9 is overexpressed in various human cancers and linked to TME immunosuppression and therapeutic resistance." (PMID 40857405, 2025). "Furthermore, S100A9 has implicated in regulating cell proliferation, migration, and invasion in the context of chronic inflammation associated with cancer." (PMID 38504474, 2024). "However, in cancer, S100A9 levels have been shown to associate with poor prognosis and lack of response to immunotherapy." (PMID 39497822, 2024). "Also, CXCL1 causes an increase in TAM and MDSC, which secrete S100A9 with a pro-survival effect on cancer cells." (PMID 38673949, 2024). "Fourth, our analysis suggests that host myeloid cells may be a potential source of EV-associated S100A9 protein in plasma, instead of cancer cell-specific markers typically analysed in liquid biopsy studies." (PMID 39516397, 2023). "ER+ tumors are characterized by changes in the stromal compartment, with enrichment of endothelial cells (endo ACKR1, CXCL12, RGS5) and depletion of cancer-associated fibroblasts (iCAFs2 and myCAFs4), inflammatory monocytes (Mon S100A9), and B naive cells, compared with TNBC." (PMID 37549298, 2023). "Whether the expression of S100A8/S100A9 is a result of chronic inflammation related to cancer or plays a causative role in response to ICB therapy and patient prognosis requires further investigation." (PMID 37835599, 2023). "Moreover, exogenous GM‐Exo promoted cancer cell stemness via S100A9 in vivo, which enhanced the susceptibility of mice to AOM/DSS‐induced CAC." (PMID 31559140, 2019). "Therefore, pending additional work on larger samples of various types of inflammation-associated cancers and usage of serum levels of S100A9 for diagnosis is promising." (PMID 29795379, 2018). "However, pending additional work on larger cohorts of patients and usage of serum S100A9 in diagnosis of other virus-associated cancer are promising." (PMID 29795379, 2018). "All these evidences suggest that S100A9 might be the future candidate marker for diagnosis of inflammation-associated cancer." (PMID 29795379, 2018). "Based on its expression and potential pro-inflammatory mediator function in inflammation and cancer, S100a9 may play a key role in inflammation-associated cancer." (PMID 29326691, 2017). "S100A8 and S100A9 play pathogenic roles in cancer progression in a concentration-dependent manner." (PMID 22489132, 2012).
cancer (continued). "FTL is an inflammation marker also implicated in cancer, S100A9 is an important member of the Ca2+ signaling cascade reported to be altered in GBM tissue, and CNDP1 has been reported for its role in the regulation of the levels of carnosine, implicated as a potential drug for GBM." (PMID 23029420, 2012). "Only two studies evaluated S100A9 expression in a cancer-associated environment." (PMID 22838504, 2012). "S100A9 protein, which is recently classified as a novel damage associated molecular pattern, is released from stressed cells undergoing necrosis or secreted by living cells undergoing a stress that act as endogenous danger signal associated with infection, tissue damage and cancer." (PMID 29615081, 2018). "S100A8 and S100A9 were also found to be overexpressed in tears and saliva collected from patients with forms of cancer, but to a much greater extent (∼10‐fold enrichment) than observed in this study." (PMID 40963435, 2026). "These cells expressed pro-inflammatory genes, such as Cd74, S100a8, and S100a9, which have been shown to contribute to the progression of various cancer types." (PMID 39425000, 2025). "Tasquinimod (ABR-215050) by blocking S100A9 activity was able to sensitize cancer cells for apoptosis." (PMID 40881687, 2025). "S100 calcium binding protein A9 elevates the cancer stem-like ratio, and increasing cancer stemness contributes to resistance to therapy." (PMID 39858016, 2025). "The S100A9 protein has been observed in cancers, where it is involved in invasion, migration, and the epithelial–mesenchymal transition (EMT) by promoting matrix metalloproteinase expression through the Wnt/beta-catenin and p38 MAPK-signaling pathways." (PMID 41155408, 2025). "The heterodimer S100A8/S100A9, known as calprotectin, is involved in the immune system, but altered expression of S100 family members is also found in cancers." (PMID 41155408, 2025). "Starting from the similarities between cancer and pregnancy, researchers have studied the role of S100A9 in early pregnancy, and found that upregulated S100A9 in early pregnancy mediates trophoblast function." (PMID 41155408, 2025). "The expression of S100A8 and S100A9 is tissue- and cell-specific and is changeably enhanced in various cancer types and inflammation-related diseases." (PMID 39895787, 2025). "Recent studies have demonstrated that S100A8 and S100A9 can stimulate the proliferation, migration and invasion of most cancer types 25-27." (PMID 39895787, 2025). "We therefore conclude that other inhibitors or signaling pathways must be investigated to dismantle the potentially detrimental effects of S100A9 in initiating immune suppression in cancer." (PMID 39497822, 2024). "We therefore conclude that Paquinimod treatment blocks beneficial proinflammatory and chemotactic signals from S100A9 in cancer." (PMID 39497822, 2024). "It is worth mentioning that HBA1, S100A8 and S100A9 play important roles in mediating drug resistance in cancer cells, which also provides insights into the mechanism of drug resistance in AML." (PMID 39583114, 2024). "Among the S100 family proteins, S100A8/A9, a heterodimer composed of S100A8 and S100A9, is a notable factor that induces inflammation-mediated cancer metastasis when present at elevated levels in the extracellular environment." (PMID 39570532, 2024). "Our study found that S100A9 was differentially expressed between male and female patients in four cancer types (BRCA, DLBC, KIRP, SARC)." (PMID 39175079, 2024). "The S100A9 gene in Group I is a calcium-binding protein that is normally expressed in myeloid cells but is upregulated in inflammation and cancer." (PMID 39140365, 2024). "The phenotype changes of NK cells in ER+/HER2−BC after overexpressing S100A9 in cancer cells were evaluated by the production levels of IFN-gamma, perforin and granzyme B and cytotoxicity assay." (PMID 38713229, 2024).
cancer (continued). "Exosomes derived from MDSCs express augmented levels of S100A9 in CRC relative to healthy controls, and aberrant expression of S100A9 can be predictive for cancer development and relapse." (PMID 38741166, 2024). "By interacting with these receptors, S100A9 activates downstream signaling pathways in the target cells, influencing the development of cancer." (PMID 38713229, 2024). "The extracellular form of S100A8/S100A9 functions by modulating cellular oxidative metabolism and facilitating inflammation-to-cancer progression." (PMID 38817853, 2024). "Based on the pan-cancer analysis, we further explored the differential expression and prognosis of S100A9 in GBM." (PMID 39137310, 2024). "Our study also finds that Paquinimod treatment does not affect the generation or accumulation of suppressive Ly6G+ cells, which seems to run contrary to the consensus that S100A9 is important for MDSC development in cancer." (PMID 39497822, 2024). "This conundrum, combined with the controversy regarding the identification of MDSCs as a separate cell type or as a functional phenotype on myeloid cells, warrants further investigation into the role of S100A9 signaling and myeloid immune cells in cancer." (PMID 39497822, 2024). "The result revealed that S100A9 overexpression in cancer cells enhanced the cytotoxicity of cocultured NK-92 cells." (PMID 38713229, 2024). "Targeting S100A9 in cancer has therefore been proposed as a potential way to relieve myeloid-mediated immune suppression." (PMID 39497822, 2024). "Research from both the Gabrilovich lab and Ostrand-Rosenberg lab has identified S100A8 and S100A9 as factors which contribute to differentiating immature myeloid cells to become MDSCs and the accumulation of these cells during cancer progression." (PMID 39497822, 2024). "S100A9 has been found to influence the viability and migration of cancer cell lines by regulating the Wnt/β-catenin pathway." (PMID 39596686, 2024). "It is therefore possible that intracellular S100A9 in myeloid cells mediates opposite functions to extracellular S100A9 released by cancer cells or other immune cells, and this possibility remains to be further investigated." (PMID 39497822, 2024). "The S100A9 also plays a role in cancer progression and metastasis since it has been demonstrated to be expressed in the lungs." (PMID 39594999, 2024). "In conclusion, our study found that NK cells in ER+/HER2−BC exhibited a hypofunctional state, and overexpressing S100A9 in cancer cells improved NK cells function in ER+/HER2−BC." (PMID 38713229, 2024). "The findings above suggest that S100A9 signaling would be beneficial for the initial anti-cancer immune responses." (PMID 39497822, 2024). "Contrary to expectations based on several previous studies, we found that inhibiting S100A9 signaling using Paquinimod reduced beneficial proinflammatory and chemotactic signals in cancer." (PMID 39497822, 2024). "Our data suggested that four TFs targeting S100A9 in the male group were responsible for the upregulation of S100A9 in male patients and affected the cancer progression." (PMID 39175079, 2024). "Our study contributes to acknowledging the complex effects of S100A9 on the immune response to cancer, where early signaling appears to contribute to beneficial immune cell infiltration." (PMID 39497822, 2024). "S100A9 also exerts a role in promoting cancer cell proliferation, migration, invasion, and recurrence." (PMID 38504474, 2024). "S100 proteins, particularly S100A4, S100A7, and the S100A8/S100A9 heterodimer, are involved in cancer progression, inflammation, and metastasis through their interaction with RAGE." (PMID 39830522, 2024). "Transcriptome analysis revealed a set of significantly differentially expressed secreted genes, including AFP, MMP9, MMP-7, and S100A9, which are known regulators of cancer progression and therapeutic targets in cancer patients." (PMID 38307859, 2024).
cancer (continued). "The alarmin S100A9 has been described to induce an immune suppressive phenotype in myeloid cells during cancer, which run contrary to its role as a proinflammatory signal in infections or sterile inflammation." (PMID 39497822, 2024). "It has also been shown that S100A9 expressing MDSCs can suppress T cell response in cancer and other diseases." (PMID 39516397, 2023). "The microenvironment initiates this phenotype by responding to the presence of colonizing metastatic cells with the production of cytokines that induce S100A9 expression in the cancer cells." (PMID 36652782, 2023). "This study discovered novel PC-derived cachexigenic factors S100A8, S100A9, and S100A8/A9 heterodimer that potentially mediate muscle wasting, the hallmark of cancer cachexia, and thus have important prognostic and therapeutic implications." (PMID 37280516, 2023). "Prior research in both solid tumors and hematological cancers already demonstrated an important role of S100A9 in cancer progression and drug resistance (e.g. chemotherapy, radiotherapy and immunotherapy resistance)." (PMID 38110349, 2023). "Proinflammatory cytokines S100A8/S100A9/S100A11 are calcium‐binding proteins that are upregulated in human cancer." (PMID 36967480, 2023). "Several genes such as CXCR4, APQ1, TACSTD2, and S100A9 have been reported to participate in angiogenesis or are highly expressed in endothelial cells in cancer." (PMID 37626402, 2023). "Since the expression of S100A9 was reported to promote polarisation of macrophages to M1 and M2 phenotype in many cancer types." (PMID 39516397, 2023). "Those genes contributing to ‘defense response’ and ‘peptidase activity’ terms in recurrent tissues were mainly composed of a number of genes previously associated with cancer such as S100A8, S100A9, TANK, or ADORA2B." (PMID 37177979, 2023). "The increased percentage of double fluorescent mCherry+/GFP+ cancer cells after irradiation ex vivo was abrogated when S100A9 was targeted." (PMID 35411077, 2022). "Here, we report that brain metastatic cancer cells from different primary tumors are induced to highly express S100A9 within the brain microenvironment, which mediates resistance to radiotherapy by downstream activation of NF-κB." (PMID 35411077, 2022). "Remarkably, both knockdown targeting S100A9 in H2030-BrM cancer cells were sufficient to extend OS when combined with radiotherapy." (PMID 35411077, 2022). "We further validated the induction of S100A9 in cancer cells ex vivo and in vivo in experimental and human brain metastases." (PMID 35411077, 2022). "The high expression of S100A8 and S100A9 is discussed as an unfavorable prognostic factor for cancer patients." (PMID 36552040, 2022). "We found that PSCs stimulated PDAC cells to secrete S100A9, which attracted circulatory monocytes into cancer tissue and enhanced the expression of programmed death-ligand 1 (PD-L1) on macrophages." (PMID 34374812, 2022). "In this report, we identify S100A9 as a common mediator of radioresistance in brain metastasis that is induced in cancer cells by interaction with the brain microenvironment." (PMID 35411077, 2022). "Secreted S100A9 protein has also been reported to play a role in the establishment of a favorable environment for cancer growth." (PMID 34374812, 2022). "Previous reports have indicated that S100A9 acts as a secreted protein that promotes cancer development." (PMID 36041055, 2022). "Among the veritable mountain of molecules associated with cancer metastasis, S100A8/A9, a heterodimer complex of S100A8 and S100A9 proteins, is especially noteworthy." (PMID 36142212, 2022). "Metastatic cells were allocated into nine clusters, with six of them showing detectable expression levels of S100A9, in agreement with a more abundant expression in cancer cells than in the microenvironment." (PMID 35411077, 2022).
cancer (continued). "PSCs stimulated PDAC cells to secrete S100A9, which acts as a chemoattractant to attract circulatory monocytes into cancer microenvironment and induces expression of PD-L1 on macrophages." (PMID 34374812, 2022). "Recent investigations have demonstrated that S100A9 is involved in the proliferation, migration, and metastasis of various cancers." (PMID 36072966, 2022). "S100A8+S100A9+CD15+ PeCa specimens were in tendency rather invasive growing cancers (TMA TC odds ratio = 2.872, TMA IF odds ratio = 3.048) and significantly enriched in the HPV+ group of metastasizing PeCa (odds ratio = 8.444, p = 0.0232)." (PMID 36303837, 2022). "S100A9 plays an important role in malignant development and cancer progression by triggering protumor immune responses." (PMID 34157683, 2021). "S100A8/S100A9 is often upregulated in cancer and is involved in inducing a pro-inflammatory response." (PMID 33469045, 2021). "S100A9 is a member of the S100 protein which shows a potential cytokine-like function in inflammation and is expressed in some cancers, impacting carcinogenesis, cancer development, and metastasis." (PMID 34490085, 2021). "Although S100A9 have been studied in many types of cancers, the biological function in malignancies was still remains contradictory and poorly understood." (PMID 34689294, 2021). "S100a9, expressed by neutrophils and MDSCs, has previously been shown to exert immunosuppressive functions in cancer and inflammation." (PMID 34220829, 2021). "In line with S100A9 and S100A12, high blood monocyte count was shown to be associated with shorter PFS and cancer-specific survival in patients with metastases." (PMID 34067757, 2021). "S100A9, a newly identified NF-κB target gene identified in multi-type of cancer, was also demonstrated to be involved in myeloid cell differentiation into M2-like Mφ in CRC." (PMID 34093546, 2021). "Another therapeutic potential of targeting NETosis is connected to the ability of NETs to secrete the Ca2+-binding proteins S100A8 and S100A9, which are considered key players in linking inflammation and cancer." (PMID 34201758, 2021). "Many studies have found that the serum level of S100A9 is significantly increased in many types of cancer and benign biliary diseases (BBD)." (PMID 33806004, 2021). "Meanwhile, seven common genes, FOSL1, S100A9, CXCL12, ID2, PRS6KA3, AREG, and DUSP6, have been used as the target biomarkers and even the diagnostic tools in cancer therapy." (PMID 34490085, 2021). "A further study indicates that suppression of S100A8 and S100A9 in cancer cells using short hairpin RNA significantly diminished migration and invasion in culture." (PMID 33801279, 2021). "After go through the differentially expressed genes list and reviewing the relevant literatures, we found that S100A9 exhibits a broad range of biological functions involving in various cancer progression." (PMID 34689294, 2021). "In turn, S100A9 was found to be responsible for increased survival of the cancer cells in mice treated by doxorubicin and cyclophosphamide." (PMID 33585241, 2020). "Previous studies have shown that members of the S100 protein family are associated with various cancer entities; both S100A8 and S100A9 can promote proliferation, survival, and metastasis." (PMID 32503348, 2020). "S100A9 is considered as a driving force for migration and invasion in cancer cells through a number of signaling pathways including ERK1/2, MAPK, JNK, and NF-kB." (PMID 32793473, 2020). "With regard to up-regulated DEGs enriched in immune response, it is now well-established that FGR, CXCL1, NLRC4 and S100A9 influence the pathogenesis of cancer by modulating immune responses and promoting progression, aggressiveness and cell survival 32-35." (PMID 32922167, 2020). "In cancer, IL-1β and S100A9 have been involved in the mobilization of pro-tumoral immature neutrophils with immune suppressive functions." (PMID 32466264, 2020).